ST3GAL3 (ST3 beta-galactoside alpha-2,3-sialyltransferase 3)
Diseases named in the same sentence as ST3GAL3 in open-access papers (continued):
Sharing a sentence is not in itself a finding about the gene and the disease.
Epileptic encephalopathy (1 paper, 2023). A condition in which epileptiform abnormalities are believed to contribute to the progressive disturbance in cerebral function. "Previous reports have found that ST3GAL3 variants are linked to developmental and/or epileptic encephalopathy (DEE); to date, it has only been reported in nine patients." (PMID 37938134, 2023). "In addition, we have compared our findings in this case with those of previous research, summarizing the DEE phenotype and associated ST3GAL3 genetic characteristics, to further highlight that ST3GAL3 gene defects may be the causal agent in patients with epileptic encephalopathy." (PMID 37938134, 2023).
Epileptic spasm (1 paper, 2023). A sudden flexion, extension, or mixed extension-flexion of predominantly proximal and truncal muscles that is usually more sustained than a myoclonic movement but not as sustained as a tonic seizure. "Seizures related to ST3GAL3‐related DEE often occur in infancy and may present as epileptic spasms." (PMID 37067065, 2023).
glycosylation disorders (1 paper, 2025). "Other examples of glycosylation disorders are pathogenic variants of ST3GAL3, which encodes the Golgi transmembrane enzyme sigleosyltransferase ST3Gal-III." (PMID 39858526, 2025).
hyperreactivity (1 paper, 2023). "TRPM4 is associated with cold airway hyperreactivity, TMEM102 and CD200R1 are involved in Th cell activation, and ST3GAL3 and B3GNT7 are associated with protecting the distal airways against destruction." (PMID 38203236, 2023).
learning disabilities (1 paper, 2021). "While ADHD is frequently associated with reduced cognitive performance, including impaired working memory that results in learning disabilities, ST3GAL3 was also implicated in by a GWAS meta-analysis on general cognitive function." (PMID 34650588, 2021). "In this regard, male HET mice showed impaired memory in the place learning task and, it is well known that learning disabilities are frequently observed in ADHD patients and also supported by a GWAS meta-analysis implicating ST3GAL3 in general cognitive function." (PMID 34650588, 2021).
malignant meningiomas (1 paper, 2024). "In contrast, ST3GAL1 and ST3GAL3 were highly expressed in the malignant meningioma—HKBMM and IOMM-Lee." (PMID 38274327, 2024).
meningioma (1 paper, 2024). A generally slow growing tumor attached to the dura mater. "High expression of ST3GAL1 and ST3GAL3 in malignant meningiomas may play an essential role in the progression and invasion of this malignancy." (PMID 38274327, 2024). "In the GEO database, mRNA expression of ST3GAL4 was significantly decreased in grade II and III meningiomas (P < 0.05), while the others (ST3GAL1, ST3GAL3, ST3GAL6, ST6GAL1, and ST6GALNAc1) were not." (PMID 38274327, 2024).
Miscarriage (1 paper, 2021). A pregnancy that ends at a stage in which the fetus is incapable of surviving on its own, defined as the spontaneous loss of a fetus before the 22th week of pregnancy. "To identify potential key enzymes related to Lewis antigens in miscarriage, we evaluated the expression patterns of three α-2,3 sialyltransferases, ST3GAL3, -4, and -6, which act on the N-Acetyllactosamine structure (Galβ1,3/4GlcNAc) to create sLeA/X and related sialofucosylated glycans." (PMID 34135905, 2021).
ovarian tumor (1 paper, 2023). "We observed 24 ABH antigen synthesis‐related genes in which five genes (FUT1, FUT2, FUT3, B3GNT3, and B3GNT2) were up‐regulated and three genes (ST3GAL3, ST3GAL4, and B3GALT2) were down‐regulated in ovarian tumor tissue versus adjacent tissues in all samples." (PMID 36415180, 2023).
rheumatoid arthritis (1 paper, 2022). A chronic, systemic autoimmune disorder characterized by inflammation in the synovial membranes and articular surfaces. "This study is aimed at investigating the role of β-galactoside-α2,3-sialyltransferase III (ST3GAL3) in fibroblast-like synoviocytes (FLS) in rheumatoid arthritis (RA), as well as its potential mechanism of action." (PMID 36405992, 2022).
cancer (20 papers, 2010 to 2025). A tumor composed of atypical neoplastic, often pleomorphic cells that invade other tissues. "Aberrant expression of ST3GAL1 and ST3GAL3 was found in different cancer types and has been associated poor prognosis and cancer progression." (PMID 38274327, 2024). "α2,3-Sialyltransferases ST3GAL2 and ST3GAL3 are responsible for sialyl-Lewis(x) synthesis, which is associated with cancer aggressiveness." (PMID 35071226, 2021). "The overexpression of ST3Gal3 has been linked to cancer progression and is involved in creating ligands that can induce apoptosis in eosinophils." (PMID 29912148, 2018). "The expression of ST3Gal3 has been also shown to be increased in a variety of cancers including pancreatic and gastric." (PMID 29912148, 2018). "Abnormal expression of ST3GAL3 develops in many diseases, especially human cancers." (PMID 36405992, 2022). "ST3Gal3 is involved in the synthesis of sLeA (also known as carbohydrate antigen 19-9 [CA19-9]) and sLeX, which are expressed in different types of cancer, and have been linked to cancer progression and poor prognosis, eventually by selectin-mediated invasion and metastasis of tumor cells." (PMID 34975914, 2021). "Additionally, Ashkani and colleagues reported the identification of glycosyltransferases gene expression profiles able to classify cancer types employing expression data taken from cancer patient samples in TCGA and, remarkably, ST3GAL3 gene was found to be highly overexpressed in GBM." (PMID 33447350, 2020). "Recently, an alternative approach was followed in which the glycosyltransferases ST3GAL2, ST3GAL3, B4GALT5, and B3GALT4 were suggested as a further predictor in identifying GD2-positive phenotypes in cancer patients." (PMID 36551537, 2022).
tumor (14 papers, 2010 to 2025). "Elevated St3gal3 levels are associated with poor prognosis in HGSOC by contributing to an immunosuppressive TME characterized by increased infiltration of pro-tumor macrophages and reduced CD8+ T-cell activity." (PMID 40330466, 2025). "The expression of ST3Gal3 has been associated with tumor progression, differentiation, and metastasis in extrahepatic cholangiocarcinoma and secondary tumor recurrence in gastric cancer." (PMID 38958800, 2024). "Other than this, ST6Gal1 and ST3Gal3 expression has also shown an association with secondary local tumor recurrences in gastric cancer (p = 0.005; p = 0.012)." (PMID 36547200, 2022). "Members of this family are involved in the synthesis of gangliosides (ST3Gal2 and 5), and the tumor-associated sialyl-T (ST) (ST3Gal1) and sialyl-Lewis (ST3Gal3, 4, and 6) antigens." (PMID 34975914, 2021). "Further, knockout of St3gal3 sialyltransferase compromised the metastatic efficiency of tumor cells by reducing α-2,3-linked sialylation." (PMID 31872800, 2019). "In cervical neoplasia, an increased expression of the sialyltransferase genes ST6GAL1 and ST3GAL3 has been reported as well as increased sialic acid and the tumour antigens sLe(X), Tn and sTn." (PMID 30038662, 2018). "Similar results were obtained with patient-derived primary-tumor samples; while overexpression of ST3Gal3/6 was detected in one MYCN-amplified patient sample (NB1), overexpression of ST3Gal4 was found in the other (NB2)." (PMID 30344930, 2018). "ST3GAL3 could serve as a marker gene for circulating tumor cells (CTCs) in patients with BC receiving adjuvant therapy." (PMID 35444644, 2022). "Focusing on glycosyltransferases expression in tumor tissues, we observed two distinct expression clusters, segregating FUT3, FUT4, FUT6, and ST3GAL4 transcripts, from FUT7, FUT9, ST3GAL3, and ST3GAL6." (PMID 39508360, 2025). "Knockdown or inhibition of St3gal3 reprograms this environment by boosting immune cell infiltration, enhancing the presence of cytotoxic CD8+ T cells, and repolarizing TAMs from a tumor-promoting M2-like phenotype to an antitumor M1-like state." (PMID 40330466, 2025).
neurodevelopmental disorder (3 papers, 2021 to 2025). A behavioral and cognitive disorder with onset during the developmental period that involves impaired or aberrant development of intellectual, motor, or social functions. "Defects in the Golgi enzyme beta‐galactoside‐alpha‐2,3‐sialyltransferase‐III (ST3Gal‐III) caused by biallelic ST3GAL3 gene variants are associated with human neurodevelopmental disorders." (PMID 37938134, 2023).
infection (2 papers, 2018 to 2023). The state of being infected such as from the introduction of a foreign agent such as serum, vaccine, antigenic substance or organism. "However, only the infection with G9P was associated with a significant downregulation of the expression of genes encoding ST3Gal (ST3Gal2, ST3Gal3, and ST3Gal6) and ST6Gal (ST6Gal1) sialyltransferases." (PMID 37515094, 2023).
diseases of the central nervous system (1 paper, 2025). "These include genes involved in neurodegeneration (EIF5), diseases of the central nervous system (IPO13, ST3GAL3), tobacco addiction (CHRNB4, PSMA4), fatty acid metabolism (ACSBG1), and skin conditions (HYI, ELOVL1)." (PMID 40074595, 2025).
ST3GAL3 also shares sentences with these, for which no sentence is quoted: behavioral disorders (2 papers); cervix squamous cell carcinoma (2); developmental and epileptic encephalopathy (2); eosinophilia (2); Ataxia (1); autism spectrum disorder (1); cervical intraepithelial neoplasia (1); cognitive (1); Dystonia (1); gastrointestinal carcinoma (1); infantile epilepsy (1); infantile epileptic encephalopathy (1); inflammation (1); Lennox-Gastaut syndrome (1); liver cancer (1); lymph node metastasis (1); melanoma (1); microcephaly (1); movement disorder (1); oral cancer (1); ovarian serous carcinoma (1); Peters plus syndrome (1); Seizure (1); squamous intraepithelial lesion (1).